FGFR2 (fibroblast growth factor receptor 2)
Diseases named in the same sentence as FGFR2 in open-access papers (continued):
Sharing a sentence is not in itself a finding about the gene and the disease.
gastric cancer (continued). "In this study, we applied a kinome-wide CRISPR/Cas9 knockout assay to systematically investigate kinases as determinants of sensitivity to FGFR inhibition in KatoIII cells, a gastric cancer cell line with FGFR2 amplification." (PMID 31076567, 2019). "There are several reports where long-term FGFR2-inhibitor exposure of sensitive FGFR2 amplified gastric cancer cell lines and patient-derived xenograft (PDX) models lead to resistance." (PMID 31076567, 2019). "Previously, a multikinase small-molecule inhibitor, AZD2171, was reported to have antitumor activity against gastric cancer xenografts overexpressing FGFR2." (PMID 29420662, 2018). "Intratumoral heterogeneity is commonly observed in gastric cancer and has been observed for FGFR2 gene copy number and for FGFR2 mRNA and protein expression." (PMID 28852882, 2018). "Previous studies have reported FGFR2 gene amplification in 3.6–9% of gastric cancer cases, which is in line with our findings." (PMID 28852882, 2018). "In line with previous reports we find here FGFR2 mRNA expression and gene amplification to be heterogeneous in gastric cancer tissue." (PMID 28852882, 2018). "Given the high medical need in gastric cancer and the high interest in FGFR2 as a target for gastric cancer, we set out to investigate FGFR2 in a larger cohort of Japanese gastric cancer patients." (PMID 28852882, 2018). "FGFR2 amplification is detected in approximately 3% to 10% of gastric cancers and correlates with a poor prognosis for patients." (PMID 29420662, 2018). "To determine the FGFR2 expression levels in gastric cancer samples and the intratumor heterogeneity of FGFR2, we used the mRNA in situ hybridization technology RNAscope, in which 718 samples of 1036 were successfully analyzed." (PMID 28852882, 2018). "Another potent selective FGFR inhibitor is AZD4547, which has been tested in a phase II clinical trial for patients with advanced breast, lung and gastric cancer harboring FGFR1 or FGFR2 amplifications." (PMID 30181810, 2018). "In conclusion, we demonstrated that activation of FGFR2 signaling plays a key role in colorectal and gastric cancers harboring FGFR2 amplification and regorafenib effectively blocks FGFR2 signaling and exhibits antitumor activity." (PMID 29573334, 2018). "The overexpression of FGFR2 was detected in up to 10% of gastric cancers and in 4% of triple-negative breast cancers." (PMID 30577533, 2018). "We also correlated FGFR2 gene amplification and FGFR2 mRNA expression with patient outcome to further investigate the biological significance of FGFR2 in gastric cancer." (PMID 28852882, 2018). "Twelve gastric cancer patients showed very strong FGFR2 mRNA expression with dense clusters of the RNAscope signal visible under a 1× objective." (PMID 28852882, 2018). "FGFR amplification has been reported in various cancers, including FGFR1 amplification in estrogen receptor‐positive breast cancer and squamous cell lung cancer, and FGFR2 amplification in triple negative breast cancer and gastric cancer." (PMID 29573334, 2018). "Gastric cancer patients with tumors that had an FGFR2 mRNA expression score of 4 had shorter RFS compared with score 0–3 patients." (PMID 28852882, 2018). "In our study, gastric cancer patients with high FGFR2 mRNA expression with a score of 4 had shorter RFS compared with patients with tumors that had a score of 0–3." (PMID 28852882, 2018). "Our study is the largest so far to report FGFR2 detection by RNAscope compared to gene amplification by DISH in gastric cancer." (PMID 28852882, 2018). "More recently, mRNA in situ hybridization, FISH, and immunohistochemistry (IHC) for the assessment of FGFR2 in gastric cancer have been directly compared." (PMID 28852882, 2018). "To further investigate FGFR2 as a target in gastric cancer, we were interested in the intra-tumor heterogeneity of the FGFR2 mRNA expression and gene amplification and the association with clinical outcome." (PMID 28852882, 2018).
gastric cancer (continued). "We found only 0.4% of the investigated gastric cancer cases with high and homogeneous FGFR2 expression, limiting the value of FGFR2 as a target in gastric cancer." (PMID 28852882, 2018). "FGFR2 gene was originally identified as an amplified DNA sequence from the gastric cancer cell line Kato III, and subsequent efforts identified FGFR2 amplification in 3% to 10% of primary gastric cancers." (PMID 29420662, 2018). "FGFR2 mRNA expression was heterogeneous across and within the gastric cancer tissue sample; only 3 of the 718 samples analyzed (0.4%) showed a high (score 3 or 4) FGFR2 mRNA expression level in more than 80% of the tumor cells." (PMID 28852882, 2018). "Although we found a differential expression of EGFR, FGFR2, KLF4, DNMT1 and AGO4 in gastric cancer samples, only FGFR2 overexpression was statistically significant (P = 0.0449)." (PMID 29719612, 2018). "We used in situ techniques to investigate FGFR2 mRNA expression and gene amplification in a large cohort of 1036 Japanese gastric cancer patients." (PMID 28852882, 2018). "Gastric cancer patients who had an FGFR2 mRNA expression score of 4 had a shorter RFS compared to patients with a sample score of 0–3." (PMID 28852882, 2018). "Preclinical studies in gastric cancer cell lines such as SNU-16 have shown impressive efficacy of anti-FGFR2 targeted agents." (PMID 28852882, 2018). "We wanted to investigate both FGFR2 gene amplification and mRNA expression as biomarkers in gastric cancer." (PMID 28852882, 2018). "Gastric cancer cell lines with FGFR2 amplifications show evidence of ligand-independent signaling and are highly sensitive to FGFR inhibitors." (PMID 28030802, 2017). "Further validation is warranted to obtain a better clinical understanding of FGFR2 amplification in patients with gastric cancer treated with palliative chemotherapy." (PMID 27802183, 2017). "We determined the presence of FGFR2 amplification by using the qPCR-based gene copy number assay, and found that FGFR2 amplification was present in 4.9% of the patients with metastatic or locally advanced unresectable gastric cancer." (PMID 27802183, 2017). "Massive previous clinical and experimental evidences demonstrated that FGFR2 is an unfavorable prognostic biomarker and antibodies targeting FGFR2 can suppress gastric cancer progression in vivo and in vitro." (PMID 28002800, 2017). "The presence of FGFR2 amplification was assessed in formalin-fixed, paraffin-embedded tissues using a quantitative PCR-based gene copy number assay with advanced gastric cancer cohorts." (PMID 27802183, 2017). "Poor treatment response represents a substantial concern in patients with gastric cancer carrying multiple FGFR2 gene copies." (PMID 28122360, 2017). "Considering the high expression of this receptor in some tumours, phase II studies are evaluating the efficacy of dovitinib (TKI258), a small FGFR2 inhibitor, on patients with FGFR2 amplification positive gastric cancer." (PMID 29094049, 2017). "AZD4547 is currently under a Phase II clinical trial to assess its activity in patients with FGFR1 or FGFR2 amplified breast, squamous lung, and stomach cancer whose cancers have progressed following previous chemotherapy (NCT01795768)." (PMID 28030802, 2017). "Preclinical models have shown that FGFR2 signaling activation due to FGFR2 amplification is an essential driver for a subset of gastric cancers." (PMID 28629429, 2017). "With the linked read WGS data from each metastatic site, our analysis identified a number of unique SV events in the chromosomal region from 10q23.31 to 10q26.13 that harbors the FGFR2 gene, a gastric cancer driver." (PMID 28629429, 2017). "Tyrosine kinase inhibitors have been shown to decrease survival of gastric cancer cells with FGFR2 amplifications in vitro." (PMID 29152066, 2017).
gastric cancer (continued). "In the ongoing clinical trial NCT01795768 (a proof of concept Phase II Trial for AZD4547) the authors identified that all of the FGFR2 amplified gastric cancers that responded to therapy had elevated levels of circulating cell free plasma DNA." (PMID 28030802, 2017). "Similar findings demonstrating intra-tumor and intra-sample heterogeneity of receptor tyrosine kinase amplification (including HER2, EGFR and FGFR2) expression in gastric cancer, have previously been reported." (PMID 29340092, 2017). "Using a three-dimensional organoid tissue model, we functionally validated the metastatic potential of an FGFR2 amplification in gastric cancer." (PMID 28629429, 2017). "In particular, an increase in the FGFR2 copy number was reported in cases of breast cancer and poorly differentiated gastric cancer." (PMID 27802183, 2017). "In conclusion, CD44 and FGFR2 maintain stemness in gastric cancer by differentially regulating c-Myc transcription." (PMID 27107424, 2016). "This is the first demonstration that the IGF signal transduction pathway is active in FGFR2-amplified gastric cancer cells." (PMID 27437872, 2016). "Nearly 40% of all gastric cancers (GCs) have genetic alterations in at least one of the FGFR2, KRAS, EGFR, ERBB2, and MET signaling axes and FGFR2 is the most frequently amplified component." (PMID 27107424, 2016). "FGFR2 amplification has been reported in 4.1–7.2% of gastric cancer cases, and in 4.0% of triple-negative breast cancer cases." (PMID 26933914, 2016). "FGFR2 amplification occurs in 3–10 % of primary gastric cancers, and has been reported to be more frequent in the undifferentiated diffuse subtype." (PMID 25407459, 2016). "To investigate the mechanisms of resistance to selective FGFR inhibitors, we established three FGFR2-amplified SNU-16 gastric cancer cell lines resistant to AZD4547, BGJ398, and PD173074, respectively." (PMID 25407459, 2016). "Dovitinib is currently being tested in a phase II trial as monotherapy in patients with metastatic or unresectable gastric cancer with either FGFR2 amplification or polysomy (ClinicalTrials.gov identifier: NCT01719549)." (PMID 25576915, 2015). "In fact, FGFR2 was first identified in a gastric cancer cell line, and it is preferentially amplified/overexpressed in the diffuse type of gastric cancer, which correlates with poor prognosis, at least in a Japanese population." (PMID 26224133, 2015). "Fibroblast growth factor receptor 2 (FGFR2)-targeted therapy has attracted considerable attention as novel anticancer agents in gastric cancer (GC)." (PMID 25576915, 2015). "To validate the prevalence of FGFR2 amplification in diffuse versus intestinal gastric cancers, we analyzed 37 diffuse and 27 intestinal subtype primary gastric tumor samples with digital PCR." (PMID 25315765, 2014). "Recently, a phase II study was designed to assess the activity of the FGFR inhibitor AZD4547 in patients with FGFR1- and FGFR2-amplified breast, squamous lung, or stomach cancers, whose cancers had progressed following previous chemotherapy (NCT01795768)." (PMID 25171497, 2014). "We confirmed strong IHC reactivity in the NCI-H716 xenograft and with an FGFR2 amplified gastric cancer tumor." (PMID 24968263, 2014). "The level of FGFR2 activation in NCI-H716 cells was similar to levels seen in the FGFR2 amplified SNU16 gastric cancer cell line." (PMID 24968263, 2014). "In support of its role as a candidate driver, FGFR2 amplification is present in a number of gastric cancer cell lines and subsequently reported in various gastrointestinal malignancies such as esophageal adenocarcinoma." (PMID 25315765, 2014). "FGFR2 is amplified in breast and gastric cancer, and we report here the first characterization of FGFR2 gene amplification in colorectal cancer in the NCI-H716 colorectal cancer cell line." (PMID 24968263, 2014).
gastric cancer (continued). "As a new candidate for a ‘driver gene’ in gastric cancer, FGFR2-targeted therapy has shown great potential in the treatment of gastric cancer." (PMID 25171497, 2014). "Deep-sequencing of a primary tumor and metastasis from a single patient, and functional validation in culture, reveals that TGFBR2 and FGFR2 act as drivers of gastric cancer." (PMID 25222187, 2014). "Breast and gastric cancer cell lines harboring FGFR2 amplification are highly sensitive to FGFR2 inhibitors in preclinical models, and amplification in both breast and gastric cancer is strongly associated with poorly differentiated, late stage tumors." (PMID 24968263, 2014). "Various genetic alterations occur within FGFR2 in endometrial, ovarian, breast, lung and gastric cancer that are thought to promote tumourigenesis." (PMID 24151975, 2013). "FGFR2 gene amplification in breast and gastric cancer results in overexpression of FGFR2 and activation of signalling." (PMID 24151975, 2013). "FGFR2 is frequently amplified in gastric cancer cell lines, especially in poorly differentiated type cells and amplification confers hypersensitivity to FGFR inhibitors." (PMID 23426935, 2013). "In conclusion, we found that FGFR2 amplification was observed in gastric cancer at a frequency of about 4.1%, and a copy number assay was a powerful tool for screening for FGFR2 amplifications using FFPE samples." (PMID 22240789, 2012). "Our results strongly encourage the development of FGFR-targeted therapy for gastric cancers with FGFR2 amplification." (PMID 22240789, 2012). "Next, FGFR2 amplification was evaluated using the copy number assay in 267 FFPE samples of primary gastric cancer specimens." (PMID 22240789, 2012). "In this report, we retrospectively studied these issues using formalin-fixed, paraffin-embedded (FFPE) samples in patients with gastric cancer who underwent surgery in an attempt to advance FGFR2-targeted therapy for gastric cancer." (PMID 22240789, 2012). "We plan to conduct a prospective study in a cohort of Japanese patients with FGFR2-amplified gastric cancers." (PMID 22240789, 2012). "Among the patients with FGFR2 amplification, the histologies of two cases were intestinal-type gastric cancer and one was unclassified type, while the others were diffuse-type." (PMID 22240789, 2012). "The copy number assay revealed that 4.1% (11 out of 267) of the gastric cancers harboured FGFR2 amplification." (PMID 22240789, 2012). "Our results warrant strong consideration of the development of FGFR inhibitors for the treatment of gastric cancers with FGFR2 amplification." (PMID 22240789, 2012). "Interestingly, FGFR2-positive circulating tumor cells have recently emerged as a promising non-invasive biomarker in gastric cancer." (PMID 41584352, 2026). "FGFR2 overexpression via immunohistochemistry (IHC) is observed in 31–61% of gastric cancer cases and correlates with aggressive tumor characteristics such as advanced T stage, increased lymph node metastasis, and reduced overall survival rates, highlighting its potential as a therapeutic target." (PMID 39195304, 2024). "FGFR2 is recognized as a valuable therapeutic target in gastric cancer." (PMID 39195304, 2024). "As we advance, the dynamic landscape of gastric cancer treatment demands continued investigation into FGFR2’s molecular mechanisms and therapeutic potential, promising a future where more personalized and effective treatment options are available for patients battling this malignancy." (PMID 39195304, 2024). "FGFR2 amplifications and mutations are common in gastric cancer, especially in the diffuse subtype, with overexpression noted in 31–61% of cases." (PMID 39195304, 2024). "Moreover, the overexpression of FGFR2b was also frequently seen in metastatic lymph node tissue; therefore, both primary and metastatic gastric cancer tissue should be examined to select patients with GC for treatment with FGFR2 inhibitors." (PMID 37510761, 2023).
gastric cancer (continued). "In addition, they examined patients with FGFR2-amplified advanced gastric cancer identified by ctDNA sequencing who received FGFR inhibitors." (PMID 37509254, 2023). "MET KDD was exclusively found in lung cancer, while FGFR2 KDD was first observed in gastric cancer." (PMID 36325957, 2023). "FGFR2 amplification is the most common genetic alteration of FGFR genes in gastric cancer." (PMID 36416959, 2023). "MiR‐381‐3p, miR‐494, miR‐5701, and miR‐519e‐5p also directly target FGFR2 to inhibit its expression and gastric cancer progression, while methyl‐CpG‐binding domain protein 1 and histone deacetylase 3 bind to form a complex that inhibits miR‐5701 expression, thereby restoring FGFR2 levels." (PMID 37750089, 2023). "While FGFR2 amplification in gastric carcinomas had a prognostically unfavorable effect in the primary gastric cancer group (p = 0.005), which was not detectable in the neoadjuvant treated group, this effect was not measurable in any subgroup of esophageal adenocarcinomas." (PMID 36416959, 2023). "Phosphorylation of GSK3β was identified as a potential target downstream of ILK whose inhibition in cooperation with AZD4547 might increase the effectiveness of FGFR inhibitors against FGFR2-amplified gastric cancers." (PMID 36497228, 2022). "FGFR2 was first reported to relate to early-onset gastric cancer." (PMID 35498538, 2022). "FGFR2 is also a potential target for TTCs, with some gastric cancers overexpressing the protein." (PMID 36726355, 2022). "This strategy effectively removes DNA fragments and traps intact genomic DNA as well as intact circular ecDNA, as evidenced by removal of DNA size markers as well as successful fractionation of known FGFR2 ecDNAs from stomach cancer SNU16 cells by CRISPR-CATCH after applying electrodepletion." (PMID 36253572, 2022). "In gastric cancer, it could be shown that only homogenous FGFR2 gene amplification led to FGFR2 overexpression and, thus, to a treatment benefit." (PMID 36231142, 2022). "In gastric cancer xenograft models, tumor growth was inhibited after a single dose of FGFR2-TTC." (PMID 36726355, 2022). "Only FGFR2 enriched in the young gastric cancer patients (FDR = 0.022)." (PMID 35498538, 2022). "FGFR2 was an interesting potential therapeutic target of gastric cancer." (PMID 35498538, 2022). "Clinicopathologic significance of these two FGFR2 subtypes in gastric cancer remains to be known." (PMID 33633310, 2021). "Meanwhile, C-terminal truncation of FGFR2 showed transforming ability in gastric cancer." (PMID 33106918, 2021). "Examples include clinical trials in HER2 positive gastric cancer, the Viktory umbrella trial in gastric cancer, the approval of targeted therapies for cholangiocarcinomas with FGFR2 fusions or rearrangements, or the use of a triple targeted therapy in BRAF mutated colon cancer." (PMID 34637026, 2021). "A phase III study demonstrated an ORR of 19% in late‐line gastric cancer with FGFR2 inhibitor." (PMID 33655556, 2021). "For example, overexpression of FGFR2 could promote the proliferation and survival of gastric cancer cells through activating MAPK/ERK and PI3K/AKT signaling pathways." (PMID 31894857, 2020). "FGFR2 is overexpressed on macroscopic type-4 gastric cancer." (PMID 31703077, 2019). "Whilst not a gatekeeper mutation, a case report of a patient with FGFR2 amplified gastric cancer who responded to LY2874455, reported a resistance conferring FGFR2-ASCL5 fusion gene on post-progression biopsy." (PMID 35582593, 2019). "Moreover, nine selective FGFR inhibitors are now in development for the treatment for gastric cancer with FGFR2 amplification." (PMID 31601997, 2019).